H2BC7 (H2B clustered histone 7)
Description:
Core component of nucleosome. Nucleosomes wrap and compact DNA into chromatin, limiting DNA accessibility to the cellular machineries which require DNA as a template. Histones thereby play a central role in transcription regulation, DNA repair, DNA replication and chromosomal stability. DNA accessibility is regulated via a complex set of post-translational modifications of histones, also called histone code, and nucleosome remodeling. Has broad antibacterial activity. May contribute to the formation of the functional antimicrobial barrier of the colonic epithelium, and to the bactericidal activity of amniotic fluid.
Synonyms: H2B/g; H2BFG; HIST1H2BF
Gene: Protein-coding gene on chromosome 6 (26,199,516 to 26,199,988, forward strand). Ensembl gene ENSG00000277224.
Subcellular location: Nucleus; Chromosome
Subcellular location (Human Protein Atlas): Nucleoplasm; Cytosol
Pathways (Reactome):
Gene expression (Transcription): B-WICH complex positively regulates rRNA expression; DNA methylation; ERCC6 (CSB) and EHMT2 (G9a) positively regulate rRNA expression; MLL4 and MLL3 complexes regulate expression of PPARG target genes in adipogenesis and hepatic steatosis; NoRC negatively regulates rRNA expression; PRC2 methylates histones and DNA; RNA Polymerase I Promoter Escape; RNA Polymerase I Promoter Opening; RUNX1 regulates genes involved in megakaryocyte differentiation and platelet function; RUNX1 regulates transcription of genes involved in differentiation of HSCs; Regulation of endogenous retroelements by KRAB-ZFP proteins; Regulation of endogenous retroelements by Piwi-interacting RNAs (piRNAs); Regulation of endogenous retroelements by the Human Silencing Hub (HUSH) complex; SIRT1 negatively regulates rRNA expression; Transcriptional regulation by small RNAs
Chromatin organization: CHD1 and CHD2 subfamily; CHD6, CHD7, CHD8, CHD9 subfamily; ChAHP complex assembly; HATs acetylate histones; HDACs deacetylate histones; Interaction of NuRD complexes with transcription factors; NuRD complex assembly
DNA Repair: Cleavage of the damaged purine; Cleavage of the damaged pyrimidine; Nonhomologous End-Joining (NHEJ); Processing of DNA double-strand break ends; Recognition and association of DNA glycosylase with site containing an affected purine; Recognition and association of DNA glycosylase with site containing an affected pyrimidine; Recruitment and ATM-mediated phosphorylation of repair and signaling proteins at DNA double strand breaks
Cell Cycle: Condensation of Prophase Chromosomes; Deposition of new CENPA-containing nucleosomes at the centromere; G2/M DNA damage checkpoint; Inhibition of DNA recombination at telomere; Packaging Of Telomere Ends
Developmental Biology: Activation of anterior HOX genes in hindbrain development during early embryogenesis; Chromatin modifications during the maternal to zygotic transition (MZT); Replacement of protamines by nucleosomes in the male pronucleus; Transcriptional regulation of granulopoiesis
Disease: Defective pyroptosis; Dengue Virus-Host Interactions
and 18 more pathways
Gene Ontology:
Molecular function: identical protein binding; protein binding; DNA binding; structural constituent of chromatin; protein heterodimerization activity
Biological process: antibacterial humoral response; antimicrobial humoral immune response mediated by antimicrobial peptide; defense response to Gram-positive bacterium; innate immune response in mucosa; chromatin organization; nucleosome assembly
Cellular component: extracellular exosome; extracellular region; nucleus; nucleoplasm; nucleosome; chromosome
Genetic constraint (gnomAD): Loss-of-function variants: 15 observed, 6.38 expected, observed/expected ratio (o/e) 2.35. That is too few expected variants to judge how well the gene tolerates losing a copy. Missense variants: 227 observed, 175.9 expected, observed/expected ratio (o/e) 1.29, 90% interval 1.16 to 1.44. Synonymous variants: 148 observed, 73.88 expected, observed/expected ratio (o/e) 2.
Homologues: Orthologues: chimpanzee H2BC4 (100% identical). Paralogues in human: H2BC10 (100% identical), H2BC4 (100% identical), H2BC6 (100% identical), H2BC8 (100% identical), H2BC12 (99% identical), H2BC15 (99% identical), H2BC21 (99% identical), H2BC5 (99% identical), H2BC9 (99% identical), H2BC11 (98% identical), H2BC13 (98% identical), H2BC17 (98% identical), and 9 more.